LGALS3 (galectin 3)
Diseases named in the same sentence as LGALS3 in open-access papers (continued):
Sharing a sentence is not in itself a finding about the gene and the disease.
endothelial dysfunction (31 papers, 2015 to 2026). In vascular diseases, endothelial dysfunction is a systemic pathological state of the endothelium (the inner lining of blood vessels) and can be broadly defined as an imbalance between vasodilating and vasoconstricting substances produced by (or acting on) the endothelium. "A recent study has shown that patients with periodontitis had higher serum and salivary Galectin-3 levels, which are associated with endothelial dysfunction and CVD risk, than did healthy individuals." (PMID 39453923, 2024). "In conclusion, together with CRP, galectin-3 was independently associated with endothelial dysfunction in patients with CKD." (PMID 34437403, 2021). "Interestingly, galectin-3 and sEng are increased in preeclampsia a systemic syndrome associated with inflammation, endothelial dysfunction and anti-angiogenic activity." (PMID 31540324, 2019). "Galectin-3 deficiency leads to exacerbated metabolic derangement and endothelial dysfunction." (PMID 26047815, 2015). "Given that galectin-3 is involved in endothelial dysfunction, we aimed to examine the association between serum galectin-3 levels and endothelial function and the possible clinical risk factors for endothelial dysfunction measured by a digital thermal monitoring (DTM) test in patients with CKD." (PMID 34437403, 2021). "Recent investigations have provided insights into the role of galectin-3 in mediating endothelial dysfunction across various cardiovascular conditions." (PMID 39063659, 2024). "Galectin-3 emerges as a central mediator in endothelial dysfunction, exacerbating vascular inflammation and oxidative stress." (PMID 39063659, 2024). "Many studies have shown that galectin-3 contributes to macrophage differentiation, formation of foam cells, endothelial dysfunction and VSMC proliferation and migration in atherogenesis." (PMID 35053194, 2021). "An interesting finding of the present study was the significant positive correlation between serum galectin-3 and the marker of endothelial dysfunction, sFlt-1." (PMID 34439802, 2021). "A previous study showed that galectin-3 was a potential biomarker of diabetic vasculopathy, and it was involved in endothelial dysfunction that leads to the vascular complications of T2DM." (PMID 31452690, 2019). "Galectin-3 has been reported to exacerbate endothelial dysfunction via oxidized-LDL and likely through oxidized-HDL-induced LOX-1 activation." (PMID 31540324, 2019). "Overall, galectin-3-mediated endothelial dysfunction contributes significantly to the pathogenesis of diastolic dysfunction and cardiovascular diseases, underscoring its potential as a therapeutic target for mitigating vascular inflammation and improving endothelial function." (PMID 39063659, 2024). "Overall, galectin-3 might have a role in cross-talk between vascular stiffness or remodeling and myocardial remodeling and mediate the process of endothelial dysfunction; when both mechanisms occur, CVD develops." (PMID 34437403, 2021). "Therefore, galectin-3 together with CRP is associated with VRI values and is a potential endothelial function modulator and a valuable biomarker of endothelial dysfunction in patients with CKD." (PMID 34437403, 2021). "Interestingly, both galectin-3 and endoglin can be expressed as a secreted biomarker in circulation and both have been involved in endothelial dysfunction and inflammation." (PMID 31540324, 2019). "Furthermore, our findings revealed that biomarkers reflecting fibroproliferative processes (VEGF, uPAR, galectin-3, E-selectin, and surfactant protein D), endothelial dysfunction (ANG-2, PECAM-1, and ICAM-1), and D-dimer were also associated with increased mortality risk." (PMID 41217548, 2025). "Although galectin-3's relationship with cardiovascular events in CKD is less consistent, increased levels correlate with endothelial dysfunction and inflammation, suggesting its involvement in vascular pathology within CKD populations." (PMID 41235339, 2025).
endothelial dysfunction (continued). "Patients with LVNC and HFpEF had endothelial dysfunction, expressed by a lower ADAMTS13 level and ADAMTS13/vWF ratio, and the overexpression of Galectin-3." (PMID 37297827, 2023). "Highly significant positive correlations were shown between serum galectin-3 concentrations and the studied inflammatory markers, including IL-6, PTX-3, and ferritin, and the endothelial dysfunction marker, sFlt-1." (PMID 34439802, 2021).
asthma (30 papers, 2008 to 2025). "Several of these DEGs associated with Tet1 loss in AT2 cells (Il33, Areg and Bpifa1, Hspa8 and Lgals3 (also DEGs in ciliated cells)), have been previously linked to asthma." (PMID 35627266, 2022). "Airway inflammation and challenge is decreased in Galectin-3 knockout mice and intranasal administration of a plasmid encoding Galectin-3 abates chronic airway inflammation in a murine model of asthma." (PMID 21867534, 2011). "Galectin-3 is involved in various crucial mechanisms of asthma pathophysiology, such as the allergic response, eosinophil activation, and non-Th2 inflammation." (PMID 39941305, 2025). "As a result, galectin-3 holds potential as a valuable biomarker for diagnosing and monitoring asthma over time." (PMID 39941305, 2025). "Among them, galectin-3 (Gal-3), galectin-9 (Gal-9), and galectin-10 (Gal-10) are the most extensively studied in human and animal asthma models." (PMID 38785528, 2024). "PCI-34051 was reported to alleviate airway inflammation in a preclinical model of asthma by disrupting HDAC8 interaction with Galectin-3, a protein involved in inflammation and pathogenesis of asthma." (PMID 33922725, 2021). "PCI-34051 alleviated airway inflammation and disrupted HDAC8 interaction with Galectin-3, a protein involved in inflammation and pathogenesis of asthma." (PMID 33922725, 2021). "This study characterised MDM efferocytosis in asthma and examined the effect of galectin-3 on this process." (PMID 30606211, 2019). "In humans, galectin-3 levels have been reported to be lower in asthma, particularly in neutrophilic asthma compared with eosinophilic and paucigranulocytic asthma, suggesting that failed efferocytosis may be occurring as a result of a galectin-3 deficiency in the airways." (PMID 30606211, 2019). "Addition of exogenous galectin-3 significantly improved net efferocytosis (39.6 (±17.8)%) compared with untreated MDMs (baseline: 33.2 (±17.7)%; p = 0.002) in the cohort with asthma." (PMID 30606211, 2019). "Reduced levels of galectin-3 in sputum have been reported in asthma and are thought to contribute to persistence of airway inflammation through decreased macrophage efferocytosis." (PMID 30606211, 2019). "MDM galectin-3 secretion was lower in asthma (9.99 (2.67, 15.48) ng/mL) compared with the healthy controls (20.72 (11.28, 27.89) ng/mL; p = 0.044) while IL-6 and CXCL8 levels were similar." (PMID 30606211, 2019). "The proportion of MDMs with galectin-3 punctae was similar between the asthma (4.8 (0.9, 6.7)%) and healthy cohorts (4.8 (0.2, 7.3)%; p = 0.845)." (PMID 30606211, 2019). "About 40% of the participants with asthma secreted very little galectin-3 compared with the rest of the participants but were comprised of a mix of both EA and NEA participants." (PMID 30606211, 2019). "Galectin-3 modulates macrophage function in asthma, indicating a potential role for galectin-3 to reverse impaired efferocytosis in NEA." (PMID 30606211, 2019). "In this study, galectin-3 secretion by MDMs was lower in participants with asthma compared with healthy participants, while IL-6 and CXCL8 secretion was similar between the groups." (PMID 30606211, 2019). "Addition of galectin-3 significantly improved efferocytosis in asthma, particularly in NEA (37.8 (±18.1)%) compared with baseline (30.4 (±19.7)%; p = 0.012)." (PMID 30606211, 2019). "Galectin-3 is found on sputum macrophages and neutrophils in human asthma, although its participation in diverse asthma phenotype in not well-understood." (PMID 30687336, 2018). "Galectin-3 stimulates efferocytotic engulfment of apoptotic cells by airway macrophages in asthma, suggesting that elevated galectin-3 levels might be a way to rescue efferocytosis in asthma." (PMID 35281078, 2022). "However, galectin-3 levels in the sputum of asthma patients were low, thus impairing efferocytosis and allowing sustained airway inflammation." (PMID 35281078, 2022).
asthma (continued). "Galectin-3 has also been involved in the recruitment, activation, and removal of neutrophils and has been described as a potential biomarker and therapeutic target of asthma." (PMID 33936056, 2021). "However, both net efferocytosis % and MFI following galectin-3 addition were negatively correlated with sputum macrophage numbers in participants with asthma (Spearman r = − 0.594; p = 0.042 and Spearman r = − 0.671; p = 0.017 respectively)." (PMID 30606211, 2019). "In a mouse model of asthma, the absence of galectin-3 was associated with a decreased clearance of apoptotic cells and persistence of inflammation." (PMID 30606211, 2019). "In the lung, galectin-3 modulates the neutrophils recruitment in pneumonia and asthma." (PMID 30687336, 2018). "In our study, a negative correlation was found between galectin-3 levels and both FVC and FEV1, confirming that galectin-3 levels are higher during exacerbations of COPD and asthma, which are characterized by lower values of FEV1 and FVC." (PMID 39941305, 2025). "The involvement of Galectin-3 in human airways inflammatory process has been ascertained for COPD, lung fibrosis and asthma." (PMID 26430389, 2015). "Sputum from subjects with asthma (n = 87) or COPD (n = 73) and ACO (n = 68) or from smokers (n = 62) and never-smokers (n = 62) was analyzed for high mobility group protein B1 (HMGB1), heat shock protein 70 (HSP70), LL-37, S100A8, and galectin-3 (Gal-3)." (PMID 31848359, 2019). "In this study, we observed reduced MDM efferocytosis from participants with asthma and demonstrated that addition of galectin-3 could significantly improve efferocytosis in asthma but not in healthy MDMs." (PMID 30606211, 2019). "Galectin-3 levels were measured in MDM supernatant 12 days post cell isolation (and following 3–4 days of culture) prior to efferocytosis and were found to be significantly lower in asthma (9.99 (2.67, 15.48) ng/mL) compared with healthy controls (20.72 (11.28, 27.89) ng/mL; p = 0.044)." (PMID 30606211, 2019). "We hypothesised that MDMs from participants with asthma, particularly those with NEA would show reduced efferocytosis compared with healthy controls and that this defect would be reversed with the addition of exogenous galectin-3." (PMID 30606211, 2019).
colitis (30 papers, 2009 to 2025). Inflammation of the colon. "The differences in disease progression between dextran sodium sulphate-treated wild type and Galectin-3-deficient mice were investigated and confirmed in clinical settings, in 65 patients suffering from mild, moderate, and severe colitis." (PMID 31336879, 2019). "The recent reports showing that several galectin members play key pathogenic roles in animal models of colitis and galectin-3 caused macrophage activation in the induction phase of colitis in a dextran sodium sulphate animal model of colitis are in line with this possibility." (PMID 31929564, 2020). "This study investigated the effect of endogenous Galectin-9 (Gal-9), as well as the combined effects with Galectin-3 (Gal-3), in modulating disease progression in murine models of colitis, using global knockout (KO) models for Gal-3, Gal-9, and Gal-3/Gal-9." (PMID 39951917, 2025). "Experimental studies in mice with colitis have mostly provided evidence for a protective role of galectin-3." (PMID 38731984, 2024). "In both acute and chronic models of colitis, a peritoneal injection of recombinant galectin-3 significantly reduced colonic IL-6 levels." (PMID 38731984, 2024). "Administration of BMSCs in a DSS-induced colitis mice model displayed beneficial effects in healing of colonic lesions due to suppressing inflammatory phenotype of dendritic cells in a galectin-3 (Gal-3)-dependent manner." (PMID 33287220, 2020). "Galectin-3 and -4 have shown anti-inflammatory properties by inhibiting mucosal inflammation in a colitis model." (PMID 32438601, 2020). "In the recovery phase of colitis, Galectin-3 was required for the immunosuppressive function of regulatory dendritic cells (DCs)." (PMID 31336879, 2019). "During the induction phase of colitis, Galectin-3 promoted interleukin-1β-induced polarization of colonic macrophages towards inflammatory phenotype." (PMID 31336879, 2019). "Concentration of Galectin-3 in serum and stool samples of UC patients negatively correlated with clinical, endoscopic, and histological parameters of colitis." (PMID 31336879, 2019). "The cutoff serum values of Galectin-3 that allowed the discrimination of mild from moderate and moderate from severe colitis were 954 pg/mL and 580 pg/mL, respectively." (PMID 31336879, 2019). "In a mice colitis experimental model, intraperitoneally administrated galectin-3 reduced inflammation." (PMID 26885508, 2016). "Possibly transferring this observation into disease-like settings, to our knowledge, the microbiome of galectin-3 deficient mice with colitis has not yet been analyzed." (PMID 40649879, 2025). "Notably, galectin-3 levels in serum and stool of patients with ulcerative colitis negatively correlated with endoscopic and histological parameters of colitis." (PMID 37189804, 2023). "MSCs also affect DCs to substantially produce galectin 3 (Gal-3) in rodents with colitis." (PMID 36707899, 2023). "When comparing wild-type and galectin-3-deficent mice in this model for inflammatory bowel disease, galectin-3 contributed to the resolution of inflammation, and acute dextran sodium sulfate-induced colitis was ameliorated by galectin-3 treatment." (PMID 37189804, 2023). "In addition, galectin-3 knockout mice suffered from a more severe disease progression in a dextran sulfate sodium (DSS)–induced colitis model." (PMID 37000885, 2023). "Similarly, galectin-3 also showed anti-inflammatory properties by contribution to ameliorate mucosal inflammation in a murine colitis model." (PMID 33805597, 2021). "Injection of BMSCs cultured in the presence of Galectin-3 (Gal-3) in a DSS-induced colitis mice model illustrated an increase in the sera concentration of IL-10 and an improvement in BMSC-mediated polarization towards the immunosuppressive M2 phenotype of macrophages." (PMID 33287220, 2020).
colitis (continued). "Moreover, dextran sodium sulphate (DSS), which is used to induce colitis in animal models, elevated galectin-3 expression in these cells, indicating that this scenario could be relevant when intestinal barrier integrity is compromised." (PMID 40649879, 2025). "Furthermore, acute DSS-induced colitis was ameliorated by galectin-3 treatment." (PMID 38731984, 2024). "It is worth noting that serum galectin-3 levels in patients with UC showed a negative correlation with endoscopic and histological parameters of colitis." (PMID 38731984, 2024). "Furthermore, serum levels of galectin-3 in UC patients exhibited a negative correlation with both endoscopic and histological indicators of colitis." (PMID 40649879, 2025).
ischemic stroke (30 papers, 2016 to 2025). A stroke disorder caused by obstruction of blood flow to the brain, due to thrombotic (local blood clot formation) or embolic (due to a blood clot or other material traveling from another site) event. "Intriguingly, our prior research revealed that higher levels of galectin-3 in the acute phase of ischemic stroke were associated with greater risk of mortality and major disability within 3 months." (PMID 35414082, 2022). "Our previous study reported that elevated galectin-3 levels were associated with increased risk of death and major disability at 3 months after ischemic stroke onset." (PMID 35414082, 2022). "Wang's team found that high levels of serum galectin-3 can be used as a predictor of poor prognosis for ischemic stroke, independently linked to an enhanced risk of severe disability or death." (PMID 34900086, 2021). "Another study showed that galectin-3 had a role in neuro-vascular protection and functional recovery after ischemic stroke, and this effect worked through modulation of angiogenic and apoptotic pathways." (PMID 33686023, 2021). "Galectin-3 is of key importance for activation, migration and proliferation of microglia after ischemic stroke." (PMID 35053194, 2021). "The role of galectin-3 in ischemic stroke remains controversial." (PMID 36873388, 2023). "Galectin-3 protects against ischemic stroke by promoting neuro-angiogenesis." (PMID 36817116, 2023). "The relationship between galectin-3 and ischemic stroke has also been reported in recent years." (PMID 34900086, 2021). "Future studies assess pathways of lowing galectin-3 may lead to new targets for improving the prognosis of ischemic stroke." (PMID 33686023, 2021). "Interestingly, the prognostic value of galectin-3 in 3-month and 12-month in the ischemic stroke patients had been reported." (PMID 33686023, 2021). "We hypothesize that CORM-3 might reduce the release of damage-associated molecular pattern molecules (DAMPs), such as high-mobility group box 1 (HMGB1) and galectin-3 (Gal3), which have been shown to stimulate microglia after ischemic stroke." (PMID 29929562, 2018). "Based on the results of immune infiltration and single-cell analysis, the exosome-related feature genes identified in this study (LGALS3, CD14, TLR2) regulate the neuroinflammatory process following ischemic stroke through multidimensional mechanisms." (PMID 40458459, 2025). "However, in this study, we showed that galectin-3 perform better than NIH score and are additionally useful in predicting the severity and prognosis of ischemic stroke." (PMID 33686023, 2021). "In a prospective cohort study involving 2970 patients with AIS, increased galectin-3 and decreased HDL-C levels of serum were observed, what could have intensified inflammatory condition and oxidative stress after ischemic stroke." (PMID 35053194, 2021). "However, when analyzing the association between Gal-3 and mRS, the Liu (2020) results may lead to the possible source of heterogeneity because this study identified the combined effect of NT-proBNP and galectin-3 on ischemic stroke patients' clinical outcomes rather than Gal-3 alone." (PMID 36846691, 2023).